BDNF (brain derived neurotrophic factor)
Diseases named in the same sentence as BDNF in open-access papers (continued):
Sharing a sentence is not in itself a finding about the gene and the disease.
cardiac arrest (7 papers, 2008 to 2025). Cessation of breathing and/or cardiac function. "We have previously identified impaired synaptic plasticity following cardiac arrest, associated with reduced hippocampal BDNF expression." (PMID 41497411, 2025). "In pediatric models, however, a seminal study in juvenile (post-natal day 20–25) mice found lower BDNF expression 7 days after global ischemia due to cardiac arrest compared to the sham operation group." (PMID 38397427, 2024). "At 24 h after cardiac arrest BDNF transcripts, namely those containing exons 1 and 3, as well as BDNF protein are increased." (PMID 18505597, 2008). "By leveraging this period of heightened plasticity, FLX or related modulators of BDNF signaling could represent promising adjunctive strategies to enhance neurorestorative care in pediatric patients following cardiac arrest or GCI." (PMID 41497411, 2025). "Critically, memory recovery and long-term potentiation in the hippocampus in that study were associated with an increase in BDNF expression from 7 days to 30 days in rats after cardiac arrest, not with neurogenesis, suggesting a potentially important role for BDNF in recovery." (PMID 38397427, 2024). "BMMSCs that were co-transduced with the engineered lentiviruses with co-overexpression of both BDNF and VEGF along with corresponding fluorescent protein reporters were injected via jugular vein of rats that just recovered from a cardiac arrest." (PMID 28492549, 2017). "However, BDNF infusions during cardiac arrest in normothermic rats were not neuroprotective." (PMID 24578682, 2014).
Cerebral atrophy (7 papers, 2017 to 2024). Atrophy (wasting, decrease in size of cells or tissue) affecting the cerebrum. "Oh reported that the decrease of BDNF would lead to cerebral atrophy, underlie age-related synaptic loss, cognitive function decline, and in particular, increase risk for psychiatric disease." (PMID 28441774, 2017). "When neuroprotective factors, such as nerve growth factor, brain-derived neurotrophic factor (BDNF), neurotrophin 3 (NT-3), and neurotrophin 4/5 (NT-4/5) are deficient in MS patients, the influx of PBMC cells to the CNS can make up for this, slowing the rate of cerebral atrophy." (PMID 39201606, 2024). "Indeed, the silencing of miR-9 by LNA-miR-9 or FA similarly attenuated neuronal damage and cerebral atrophy in the rat hippocampus after HIBD, which was consistent with the restored expression levels of brain-derived neurotrophic factor (BDNF)." (PMID 32470970, 2020).
cerebral palsy (7 papers, 2012 to 2024). A group of disorders affecting the development of movement and posture, often accompanied by disturbances of sensation, perception, cognition, and behavior. "Studies on cerebral palsy also proved miR-1 regulation of mRNA encoding BDNF, and it has been also shown that miR-1 prevented apoptosis via Igf1 regulation." (PMID 32283635, 2020). "First, in the transcriptional biomarkers of cerebral palsy, dysregulation of nutrient signaling pathways, such as brain‐derived neurotrophic factor pathways, is responsible for the decrease in neuronal protection." (PMID 39252492, 2024). "Previous studies have shown that MALAT1 can inhibit apoptosis by upregulating BDNF expression through suppression of miR-382-3p in the central neurons of cerebral palsy mice." (PMID 37740187, 2023). "In children with cerebral palsy (CP), neuromuscular deficits and mobility impairment have a negative impact on their physical activity level and nutritional status, but whether these children have reduced BDNF concentrations is unknown." (PMID 30875771, 2019). "Vitamins B1 and B12 upregulate brain-derived neurotrophic factor (BDNF) expression and its downstream PI3K/Akt signaling pathway through the MALAT1/miR-1 axis, thereby inhibiting neuronal apoptosis and reducing nerve damage in cerebral palsy rat models." (PMID 33192306, 2020).
Cirrhosis (7 papers, 2017 to 2025). A chronic disorder of the liver in which liver tissue becomes scarred and is partially replaced by regenerative nodules and fibrotic tissue resulting in loss of liver function. "Therefore, factors other than dysbiosis and glial/microglial activation, such as systemic inflammation and BDNF may be associated with neuroinflammation in mice with hepatic branch vagotomy and cirrhosis." (PMID 34248683, 2021). "Furthermore, BDNF concentrations has been reported to be associated with impairment of physical aspects of quality of life in patients with hepatitis C, and this association is independent of drug abuse status, mental problems, treatment or cirrhosis severity." (PMID 29108028, 2017). "Conventional control vs. cirrhosis: Cirrhosis resulted in dysbiosis, hepatic/neuro-inflammation with glial/microglial activation, and low brain BDNF vs. controls." (PMID 34248683, 2021). "BDNF levels in the brain were higher but low in the liver in vagotomy + cirrhosis, likely a protective mechanism." (PMID 34248683, 2021). "Interestingly, experiments show that mice with cirrhosis have high levels of the BDNF in the liver, and hepatic vagotomy levels were found to be significantly reduced in the liver but increased in the brain." (PMID 37377968, 2023). "Vagotomy-induced lower hepatic and higher BDNF cortical expression also suggest that the neurotrophic factors may have a major role in the gut-liver-brain axis in cirrhosis." (PMID 34248683, 2021). "The occurrence of memory deficits as well as reduced levels of BDNF, CREB and IRS/PI3K/Akt have been observed in a hepatic cirrhosis-induced minimal hepatic encephalopathy model, which in turn insinuates that a positive overlap between BDNF and insulin signaling does exist." (PMID 31137621, 2019). "Our findings in early-stage PBC patients without cirrhosis contrast with limited observations in cirrhotic populations, where reduced serum BDNF levels have been reported in patients with hepatic encephalopathy." (PMID 40806277, 2025). "Our data showed that with the intact vagus, BDNF increased with cirrhosis, paralleling prior studies, but this circuit is broken with vagotomy, where cirrhosis does not lead to BDNF increase in the liver but does in the brain." (PMID 34248683, 2021). "BDNF expression increased in conventional mice with cirrhosis but not in vagotomized ones." (PMID 34248683, 2021). "BDNF was not affected by cirrhosis in the conventional state." (PMID 34248683, 2021).
cocaine use disorder (7 papers, 2017 to 2024). A substance-related disorder that involves the recurring use of cocaine despite negative consequences. "Patients with opioid and cocaine use disorders who attempted suicide were associated with a single nucleotide polymorphism (in the BDNF gene, rs7934165), suggesting a common BDNF-related pathophysiology of suicide attempts and SUD." (PMID 38069051, 2023). "This investigation uses a within-cases study of BDNF and associated factors in three suicidal phenotypes (‘any’, ‘recurrent’, and ‘serious’) of outpatients seeking treatment for opiate and/or cocaine use disorder." (PMID 33479229, 2021). "There was no genetic difference between outpatients with opiate or cocaine use disorder and UK blood donors, further supporting the absence of bias related to population stratification in our results regarding BDNF and the ‘neurotrophic pathway’." (PMID 33479229, 2021). "Although several previous studies have correlated BDNF levels to psychiatric disorders, including substance use disorders, this preliminary study is the first to evaluate the BDNF mRNA expression in lymphocytes and its relationship to FAB scores in alcohol and crack-cocaine use disorder patients." (PMID 32508693, 2020).
fragile X syndrome (7 papers, 2014 to 2026). A genetic syndrome caused by mutations in the FMR1 gene which is responsible for the expression of the fragile X mental retardation 1 protein. "This workflow linked ~ 443 of these synaptic genes to six core clusters: synapse organization, neuron development, focal adhesion, extracellular matrix (ECM), Fragile X Syndrome, BDNF signaling, and ion channel activity." (PMID 37461529, 2023). "In a mouse model of fragile X syndrome (Fmr1-knockout mice), BDNF levels are decreased in the cortex but increased in the hippocampus." (PMID 25182223, 2014).
Hyperammonemia (7 papers, 2022 to 2026). An increased concentration of ammonia in the blood. "In contrast, addition of HA-M-EV to slices from control rats induce the same alterations than hyperammonemia per se on the TNFα–TNFR1–S1PR2–IL-1β–BDNF–TrkB pathway and the IL-1β–NR2B–GluA1–GluA2 pathway." (PMID 41601700, 2026). "In the cerebellum of rats with chronic hyperammonemia to model cirrhosis, increased BDNF levels promote TrkB activation in Purkinje neurons, triggering phosphatidylinositol‐3‐kinase (PI3K) activation." (PMID 41141377, 2025). "This suggested that the altered function of the BDNF-TrkB pathway would also alter GABAergic neurotransmission in hyperammonemia and MHE." (PMID 38560359, 2024). "Hyperammonemia also increased the BDNF content in the hippocampus as analyzed using Western blot, and this increase was reversed by blocking S1PR2 or IL-1R or by inhibiting Src." (PMID 38139078, 2023). "We assessed if hyperammonemia increases the phosphorylation of p38 and the content of BDNF and if these effects are mediated by the S1PR2 → IL-1β → IL-1R → Src pathway." (PMID 38139078, 2023). "This suggests that reducing the function of the TNFR1–SP1PR2–CCL2–CCR2–BDNF pathway at any of its steps reduces BDNF levels and reverse alterations in GABAergic neurotransmission in hyperammonemia and likely in patients with hepatic encephalopathy." (PMID 36233065, 2022). "The reported results also suggest that the increased membrane expression of GABAA receptors in hyperammonemia is mediated by the BDNF–TrkB-induced increase in gephyrin and in the phosphorylation of the β3 subunit of GABAA receptors." (PMID 36233065, 2022). "Hyperammonemia-induced neuroinflammation increases BDNF and TrkB activation, leading to increased synthesis and extracellular GABA, and the amount of GABAA receptors in the membrane and chloride gradient." (PMID 36233065, 2022). "We also analyzed if the increased levels of BDNF and TrkB activation were due to the enhanced activation of the TNFR1–SP1PR2–CCL2 (monocyte chemoattractant protein-1)–CCR2–BDNF–TrkB pathway in hyperammonemia." (PMID 36233065, 2022). "Hyperammonemia-induced changes in GAD65 and GAD67, and in the membrane expression of GAT3 and of the γ2, α2, and β3 subunits of GABAA receptors were a consequence of the enhanced activation of TrkB via the increased levels of BDNF." (PMID 36233065, 2022).
malaria (7 papers, 2014 to 2024). Malaria is a serious and sometimes fatal disease caused by a parasite that commonly infects a certain type of mosquito which feeds on humans. "Our study found significantly higher BDNF levels in genotype HbCC, a variant unlike sickle-cell mutation, which provides some protection against malaria but is associated with mild hemolytic anemia and joint pain." (PMID 39749215, 2024). "Thus, rosiglitazone adjunctive therapy was associated with both elevated levels of BDNF and NGF expression and maintenance of Trk-B expression in the brains of mice infected with malaria." (PMID 24603727, 2014). "Circulating levels of S100B, Tau, UCH-L1, BDNF, and NCAM-1 have been documented in previous malaria studies." (PMID 39658124, 2024). "This drug has also been demonstrated to induce secretion of neuroprotective brain-derived neurotrophic factor (BDNF), improve neurocognitive outcomes, and reduce biomarkers of inflammation in non-severe malaria." (PMID 38410724, 2024).
osteoarthritis (7 papers, 2009 to 2025). A noninflammatory degenerative joint disease occurring chiefly in older persons, characterized by degeneration of the articular cartilage, hypertrophy of bone at the margins and changes in the synovial membrane. "Downregulation of plasma BDNF was also found in osteoarthritis patients with pain." (PMID 35061744, 2022). "However, the roles of cytokines, TGF-β1 and BDNF in humans with chronic pain in osteoarthritis remains unclear, and no comparison between plasma and central cerebral spinal fluid (CSF) has been conducted." (PMID 35061744, 2022). "TGF-β1 but not BDNF, TNF-α, or IL-8 may be an important biological indicator in the CSF of osteoarthritis patients with chronic pain." (PMID 35061744, 2022).
retinal diseases (7 papers, 2020 to 2025). "Experimental or clinical studies have shown that physical activity can be protective in neurodegenerative, mitochondrial, or retinal diseases and associated with increased serum, brain, and/or retina levels of neurotrophins such as brain-derived neurotrophic factor (BDNF)." (PMID 38540197, 2024). "Recently, exercise has been demonstrated to have protective effects in animal models of retinal diseases via multiple mechanisms, including the BDNF/TrkB signaling pathway, increased blood flow, and modulation of VEGF and its receptors." (PMID 36275903, 2022). "Retinal disease treatment consisting of BDNF administration could help in the resolution of different pathologies caused by BDNF reduction." (PMID 35269763, 2022). "This information is essential for developing BDNF-mediated neuroprotection in DR and hypoxic retinal diseases, and for improving anti-VEGF treatment for these blood–retina barrier disorders, in which VEGF is a major therapeutic target for vascular abnormalities." (PMID 34068807, 2021). "Our primary goal was to address whether VEGF played a direct role in mediating MC viability and neuroprotection through a classic neurotrophin BDNF, which is an important question in the field of neuroprotection in DR and hypoxic retinal diseases, such as AMD." (PMID 34068807, 2021). "The involvement of the BDNF-TrkB axis in the biology of sensory systems is demonstrated by the studies conducted on zebrafish which is emerging as an increasingly successful experimental model for studying hearing and balance, retinal diseases, and odor detection." (PMID 35269763, 2022).
Sleep apnea (7 papers, 2015 to 2023). An intermittent cessation of airflow at the mouth and nose during sleep is known as sleep apnea. "In this study, the authors also studied the effect of adenotonsillectomy on BDNF levels and found that BDNF levels decreased 3 months after adenotonsillectomy which was associated with the improvement in sleep-disordered breathing." (PMID 35127775, 2021). "Importantly, peripheral treatment with DCS also normalized BDNF expression in the brainstem, which may account for the improvement that we observe in sleep apneas." (PMID 28813484, 2017). "The increased locomotor activity, which is not a feature of CSD in sleep apnea, may increase neuroprotectants in the brain including SirT1 and BDNF." (PMID 26074865, 2015).
adjustment disorder (6 papers, 2015 to 2024). A category of psychiatric disorders which are characterized by emotional or behavioral symptoms that develop within 3 months of a stressor and do not persist for more than an additional 6 months after the stressor is no longer present. "Plasma BDNF has been reported to increase in patients with workplace stress‐related adjustment disorders." (PMID 37822121, 2023). "Significantly lower BDNF levels were found in those with suicide attempts in the personality disorder and adjustment disorder groups (p = 0.003, p = 0.009, respectively), but not in the depressed group." (PMID 26718989, 2015). "Methods: the pBDNF and BDNF exon I and IV promoters’ methylation levels were measured by specific immunoassays and methylation-sensitive high-resolution melting (MS-HRM) in 62 patients with adjustment disorders (AD), 79 patients with major depressive disorder (MDD) and 44 healthy controls." (PMID 39595869, 2024).
allergic rhinitis (6 papers, 2013 to 2024). Inflammation of the nasal mucous membranes caused by an IgE-mediated response to external allergens. "The study revealed a perfect linkage between BDNF rs10767664 and BDNF rs6265 and subjects with the rs10767664 A/A genotype were shown to be more susceptible to moderate-severe allergic rhinitis and had an increased plasma BDNF protein level." (PMID 30677092, 2019). "Jin and colleagues conducted a study on Chinese population to determine the association of genetic variants of BDNF (rs10767664, rs1041635, rs962369, rs12273539, rs11030121 and rs4923468) to the moderate and severe allergic rhinitis." (PMID 30677092, 2019). "Although the role of brain-derived neurotrophic factor (BDNF) in allergic rhinitis and/or nasal polyps (NPs) development has been studied, the contribution of BDNF in non-allergic NPs has not been evaluated yet." (PMID 38827877, 2024). "Both nasal NGF and BDNF expressions were reported to be significantly increased in allergic rhinitis patients compared to healthy controls after nasal allergen provocation." (PMID 23476696, 2013). "Concentrations of NGF, BDNF, and NT-3 increase dramatically in the respiratory epithelium during allergic rhinitis." (PMID 23476696, 2013). "The effect of BDNF on nerve fibers in AR has not been described; however, patients with allergic rhinitis have a greater number of vasoactive intestinal polypeptide (VIP)-positive nerve fibers in the mucosal tissue of the nasal conchae than control subjects." (PMID 37047077, 2023). "This allergen-induced increase in BDNF correlated with the maximal increase in total nasal symptom score (TNSS), suggesting an important role for this neurotrophin in modifying symptom severity in allergic rhinitis patients." (PMID 23476696, 2013).
Apathy (6 papers, 2013 to 2022). Apathy is a quantitative reduction of interest, motivation and the initiation and persistence of goal-directed behavior, where often the accompanying emotions, thoughts, and social interactions are also diminished. "Brain-derived neurotrophic factor(BDNF) levels were also analyzed since these have been associated withdepression, a condition which shares abulic features with apathy." (PMID 29213854, 2013). "We suspected that ApoE ε4 and apathy might share some common pathogenic mechanisms underlying the development of AD, such as reduced BDNF level, but directly related to each other." (PMID 33041262, 2020). "Increased BDNF in serum has been linked with specific memory deficits in AD, and decreased BDNF has been associated with the presence of APOE ε4 and apathy in subsets of AD." (PMID 32218234, 2020). "In another study, apathy and APOE ε4 were both associated with the reduced levels of brain-derived neurotrophic factor (BDNF) in AD patients, which was considered as a pathogenic event of AD." (PMID 33041262, 2020).
atrial fibrillation (6 papers, 2021 to 2024). A disorder characterized by an electrocardiographic finding of a supraventricular arrhythmia characterized by the replacement of consistent P waves by rapid oscillations or fibrillatory waves that vary in size, shape and timing and are accompanied by an irregular ventricular response. "It was reported that serum BDNF level was not related to the occurrence of atrial fibrillation." (PMID 34202148, 2021).